CCR7 (C-C motif chemokine receptor 7)
Diseases named in the same sentence as CCR7 in open-access papers (continued):
Sharing a sentence is not in itself a finding about the gene and the disease.
prostate adenocarcinoma (1 paper, 2022). "Furthermore, CCL21 activation of CCR7 promoted the migration of prostate cells via phosphorylation of p38 MAPK, suggesting a potential pathway for lymph node metastasis of prostate adenocarcinoma." (PMID 35203305, 2022).
rhabdomyosarcoma (1 paper, 2017). A rare aggressive malignant mesenchymal neoplasm arising from skeletal muscle. "From these proteins CCR7 is expressed on rhabdomyosarcoma cells and is involved in lymph node metastasis We cannot conclude if inhibition of polysialylation of CCR7 by the IBs have also contributed to the delay of metastasis." (PMID 28499450, 2017).
rosacea (1 paper, 2025). A chronic erythematous skin disorder that affects the face. "TR B cell %lymphocyte, CD25 on IgD− CD24− B cell, and HLA DR on CD14− CD16+ monocyte are risk factors for the onset of rosacea, while central memory CD4− CD8− T cell AC, CCR7 on naive CD4+ T cell, CD14+ CD16− monocyte AC, and CD62L − mDC are protective factors for the onset of rosacea." (PMID 41431076, 2025).
schizophrenia (1 paper, 2025). A major psychotic disorder characterized by abnormalities in the perception or expression of reality. "Downstream, CCR7 expression on naive CD8+ T cells mediates 33.35% of ZDHHC20’s influence on schizophrenia risk (p < 0.05)." (PMID 40842128, 2025). "This study unveils a novel causal pathway in schizophrenia, wherein DNA methylation at cg18095732 regulates ZDHHC20 expression, which in turn influences schizophrenia risk through CCR7‐mediated immune modulation." (PMID 40842128, 2025). "Our analysis revealed that CCR7 on naive CD8br cells mediates the effect of ZDHHC20 on schizophrenia, with a mediation effect of 0.0634, accounting for 33.35% of the total effect." (PMID 40842128, 2025).
scrub typhus (1 paper, 2022). Scrub typhus is a rare dust mite-borne infectious disease caused by the Orientia tsutsugamushi bacterium and characterized clinically by an eruptive fever which is potentially serious. "Taken together, our study sheds light on a CCR7/dendritic cell-mediated mechanism of early Ot dissemination and provides new insights into therapeutic and vaccine development strategies for scrub typhus." (PMID 36618364, 2022).
sialadenitis (1 paper, 2007). Sialadenitis is an infection of the salivary glands. "Studies have been conducted in which Ccr7 deficient mice develop sialadenitis." (PMID 17900348, 2007).
sickle cell disease (1 paper, 2012). Sickle cell anemias are chronic hemolytic diseases that may induce three types of acute accidents: severe anemia, severe bacterial infections, and ischemic vasoocclusive accidents (VOA) caused by sickle-shaped red blood cells obstructing small blood vessels and capillaries. "In both subjects with sickle cell disease and the mouse model, fibrocytes expressed a hierarchy of chemokine receptors, with CXCR4 expressed on most fibrocytes, and CCR2 and CCR7 expressed on a smaller subset of cells." (PMID 22442712, 2012).
synovial sarcoma (1 paper, 2021). "Taken together, sunitinib treatment of both bone and synovial sarcoma cells induced a significant upregulation of CD80, CD86, CD83 and CCR7 which are essential for full DC maturation." (PMID 33717062, 2021).
tonsillar cancers (1 paper, 2007). "There was a significant association between CCR7 immunopositivity and synchronous cervical nodal metastasis in patients with tonsillar cancer (Spearman's correlation coefficient 0.564; P<0.001)." (PMID 17687340, 2007). "This demonstrates a strong association between CCR7 expression and synchronous nodal metastasis in patients with tonsillar cancer." (PMID 17687340, 2007). "In this study, we found a striking correlation between CCR7 immunostaining in primary tonsillar cancers and the presence of cervical nodal metastases at initial diagnosis and subsequent relapse-free, overall and disease-specific survival rates." (PMID 17687340, 2007). "The correlation between CCR7 immunostaining in primary tonsillar cancers and the presence of cervical nodal metastases at initial diagnosis may be of interest in selecting patients for elective treatment of the cervical nodes in the setting of a clinically negative neck." (PMID 17687340, 2007).
transitional cell carcinoma (1 paper, 2019). A malignant neoplasm arising from the transitional epithelium, usually affecting the urinary bladder, ureter, or renal pelvis. "In another study, CCR7 knockdown by siRNA significantly abrogated the CCL21-induced migration of transitional cell carcinoma UM-UC-3 cells." (PMID 30781353, 2019).
Ureteral obstruction (1 paper, 2010). Obstruction of the flow of urine through the ureter. "Moreover, CCR7-positive fibrocytes migrate into the kidney in response to SLC/CCL21 and contribute to kidney fibrosis induced by unilateral ureteral obstruction in mice." (PMID 20126461, 2010).
WHIM syndrome (1 paper, 2011). "However, the experimental systems (i.e. cells expressing transfected mutant receptors; chemokine CCL21 that desensitizes its receptor CCR7 at low level; leukocytes from WHIM syndrome patients)." (PMID 21559528, 2011).
tumor (748 papers, 2005 to 2026). "CCR7+ IL12‐p40+ cDCs have been shown to associate with CD8+ T cells in perivascular regions of the tumour where they trans‐present IL‐15 to CD8+ T cells and are suggested to be important for the efficacy of immune‐checkpoint blockade." (PMID 40745918, 2025). "Strikingly, Il12b‐expressing cDC1s are CCR7+ and enriched at tumour borders, where they closely associate with stem‐like TCF1+ CD8+ T cells." (PMID 40745918, 2025). "They found that CCR7 expression was associated with deeper tumor invasion, advanced stage, vascular invasion, and lymph-node metastasis." (PMID 40299690, 2025). "Activated cDCs in tumours have largely been associated with a core gene expression signature that includes Ccr7 and Il12b, amongst other markers." (PMID 40745918, 2025). "Activated cDC1s and CCR7+ cDCs have long been implicated in anti-tumour immunity and, recently, in intratumoral CD8+ T cell restimulation." (PMID 39604727, 2025). "In contrast, low-risk genes (CCL17, CXCL8, FOXP3, CCR7) inhibit tumor progression by modulating immune cell infiltration and activity." (PMID 40517358, 2025). "In SELPLG-deficient tumor-infiltrating T cells, expression analysis of the same selected genes revealed that CCR7 and ITGAL were significantly upregulated in SELPLG-negative cells that infiltrated the tumor model." (PMID 41394860, 2025). "Analysis of a published dataset of human tumours similarly reveals a spatial association between CCR7+ cDC1 and stem‐like TCF1+ CD8+ T cells." (PMID 40745918, 2025). "Although CCR7 expression levels were similar in both tumour-residing or migrated CCR7+ DCs, we observed a decrease in transcripts associated with DC chemotaxis and CCR7 signalling in Ccr7_DC.2/3." (PMID 38267413, 2024). "They found that the CXCL12 and CCL21 ligands and their corresponding receptors, CXCR4 and CCR7, were highly and significantly expressed in tumor cells with lymph node metastases associated with shorter survival in this cohort." (PMID 39001456, 2024). "A possible reason for this finding is CCR7 chemotactic T- and B-cell infiltration at the tumour site, and the infiltrating T- and B-cells are involved in the immune tumour killing associated with BLCA." (PMID 38762550, 2024). "Altogether, these data underline that a subset of tumour-retained CCR7+ DCs exhibit a specific, “activated” state, which is enriched following anti-PD-L1 treatment." (PMID 38267413, 2024). "The expression of matrix metalloproteinase-9 (MMP-9) and chemokine receptor 7 (CCR7) is significantly associated with tumor invasion and metastasis." (PMID 37600570, 2023). "Mounting evidence suggests that tumour‐associated CCR7 expression mediates migration towards CCL21‐expressing lymphoid organs." (PMID 37170733, 2023). "High-grade CCR7 expression was significantly associated with a large number of tumor buds, low E-cadherin expression, and poor overall survival." (PMID 36980764, 2023). "Growing evidence suggests that the interaction between CCL21 and CCR7 in the tumor microenvironment is associated with poor prognosis in various types of human cancer." (PMID 37664721, 2023). "In CD8+ T cells, we observed upregulation of GZMA, which is indicative of effector functions, and CCR7, which is associated with increased homing to the tumor sites." (PMID 36911698, 2023). "We also found that several of the downregulated genes including Ccl1, Ccl22, Cxcl13 or Ccr7 were associated with immunosuppression and decreased anti-tumour immunity." (PMID 37516803, 2023). "CCR7 expression in various tumors has been linked to tumor cell proliferation, invasion, angiogenesis, and metastasis." (PMID 36980764, 2023). "IFNG, AC006369.1, and CCR7 were closely linked with the tumor microenvironment components (e.g., macrophages, CD4/CD8 T cells, NK cells), and immune checkpoints (notably PD1/PD-L1)." (PMID 37408777, 2023).
tumor (continued). "Inhibition of the TAK1 binding protein, TAB1, reduced CCR7 expression and tumor size in animal studies with associated suppression of lymph node invasion and metastasis." (PMID 35203305, 2022). "It further demonstrated that the progress of tumour metastasis with PTX treatment is associated with CCR7 expression." (PMID 35280672, 2022). "The expression of chemokine receptor 7 (CCR7) in tumor tissue was also enhanced and is associated with the phosphorylation of kinases ERK and p38, which induce tumor migration." (PMID 35884974, 2022). "C-C chemokine receptor type 7 (CCR7) is up-regulated in dendritic cells exposed to LL-37 that causes infiltration of CD8+ T-cells into tumor sites." (PMID 35874827, 2022). "Tumor-infiltrating dendritic cells (TIDCs), for example, initiate tumor immunity by transporting tumor-associated proteins from the tumor to the lymph nodes in a CCR7-dependent manner." (PMID 36345336, 2022). "Changes in the level of CCL19/CCR7 mRNA expression in tumor tissue can be considered as a diagnostic marker for NSCLC patients." (PMID 35160116, 2022). "It was suggested that low tumor burden, low systemic inflammation, and high product CCR7+CD45RA+ T cells were associated with durable responses." (PMID 34599413, 2022). "Cervical squamous cell carcinomas had significantly elevated CCR7 expression linked to a more invasive and larger tumor size, as well as vaginal invasion and lymph node metastasis." (PMID 35203305, 2022). "Migratory CD103+ cDC1s are one of the primary cell types capable of trafficking intact tumor-associated antigens from the tumor to the TdLN via a CCR7-dependent mechanism to initiate CD8+ T-cell priming." (PMID 35487695, 2022). "In view of the widely-discussed pro-tumor functions of M2 macrophages, we thus examined the association between CCR7 and M2 macrophages." (PMID 35904690, 2022). "Meanwhile, GPX8 mRNA expression was significantly correlated with monocyte marker CD14, dendritic-cell marker NRP1, natural killer cell marker B3GAT1, neutrophil marker CCR7, and tumor-associated fibroblast marker FAP." (PMID 36061208, 2022). "This enhancement was found to be due to mediation by VEGF-C induced CCL21 associated with tumor infiltration of naïve T cells before immunotherapy as CCR7 blockade reversed the potentiating effects of VEGF-C." (PMID 34767139, 2022). "In the tumor microenvironment, CCL21 acts as a potent chemoattractant for CCR7-positive tumor cells by binding to podoplanin on cancer-associated fibroblasts (CAFs), thereby promoting the stromal invasion of cancer cells." (PMID 35163233, 2022). "Improved anti-tumor properties have also been associated with the overexpression of CCR7 on various immune cells, e.g., NK cells but also dendritic cells, with the later also showing greater migratory abilities towards the draining lymph node." (PMID 34361107, 2021). "The CCR7 axis not only seems to play a pathogenic role by recruiting cHL tumor cells, it is also implicated in recruiting pro-tumorigenic CCR7-expressing immune cells from the circulation." (PMID 34778050, 2021). "Beyond cancer cell lymphotropism, we have disclosed that CCR7 expression is also associated to neurotropism and epidermotropism, to interstitial migration within tumor tissues, to juxta-positioning to accessory cells, and to cell survival and proliferation." (PMID 34778050, 2021). "Vahidi’s study concluded that CD8-positive memory T cells in tumor-draining lymph nodes are associated with CCR7." (PMID 34507558, 2021). "In agreement, total RNAs from skin biopsies of epidermis versus those from involved dermis of MF associated the presence of tumor cells in the dermis with the CCR7/CCL21 axis." (PMID 34778050, 2021). "Firstly, there was an association between the presence of inflammatory CCR7 expression and favourable tumor characteristics." (PMID 34588590, 2021).
tumor (continued). "Classically, the pathogenic role of CCR7 as a cancer-associated receptor in hematology has been attributed to its unique ability to drive tumor cells into the LN and other SLO." (PMID 34778050, 2021). "As such, increased CCR7 expression in certain tumor types has been associated with invasiveness and poor survival." (PMID 34503058, 2021). "Several studies indicate that high levels of CCR7 are associated with tumor metastasis and a poor clinical outcome in several cancer types, including EC." (PMID 33390169, 2021). "The ZUMA-1 study demonstrated that durable treatment response was associated with low baseline tumor burden, low systemic inflammation, and high CCR7+CD45RA+ T cell product in patients with refractory large B-cell lymphoma treated with axicabtagene ciloleucel." (PMID 34395279, 2021). "The increased expression of CCR7 on tumor cells has been shown to be associated with a poor prognosis and with the development of lymph node metastases in HNSCC." (PMID 32082401, 2020). "In the majority of these cancers, larger tumor size and deeper invasion was associated with CCR7 expression." (PMID 32340161, 2020). "CCL19 attracts mDCs and lymphocytes expressing CCR7 in T cell-rich areas, and thereby helping DCs meet tumor-associated antigen-specific T cells." (PMID 31991604, 2020). "In HCC tumors, it impaired chemotactic events associated with CCR7, limiting tumor progression and metastasis." (PMID 30894861, 2019). "For example, one study reported that high amounts of CCL21 recruit CD4+ LTi cells to tumors in a CCR7-dependent manner, which is associated with the formation of tumor-promoting lymphoid-like stroma in melanoma." (PMID 31507605, 2019). "Upregulation of CCR7 expression in SCCHN is associated with increased tumor cell survival, invasiveness, potential for metastases, and resistance to treatment, making it an important pathway to elucidate to better understand its contribution to tumorigenesis." (PMID 28858212, 2017). "This shows the involvement of the same CCL21/CCR7 axis in the tumor cell to cancer associated fibroblast recognition." (PMID 28416768, 2017). "We performed triple staining for E-cadherin, CCR7 and CD45, a pan-immune cell marker, which was used to distinguish CCR7-positive EMT cells from tumor-associated immune cells." (PMID 25961925, 2016). "Lymphatic invasion by CCR7 expressing pancreatic ductal adenocarcinoma (PDAC) cells is additionally enhanced by upregulation of CCL21 in tumor-associated lymphatics." (PMID 28036019, 2016). "Although high CCR7 expression has been implicated in tumor invasion and lymph node metastasis, the associated mechanism and downstream mediators remain incompletely defined." (PMID 26176983, 2015). "We also found a significant association between CCR7 expression and poor OS and enhanced infiltration of Tregs into primary tumor sites in GC." (PMID 26176983, 2015). "In prostate cancer, hypoxia-preconditioned MSCs produce CCL21 to attract tumor cells expressing CCR7 which is associated with enhanced lymph node metastasis of the tumor." (PMID 25110692, 2014). "SLC/CCR7 complex can cause cells to induce actin polymerization, which is closely correlated with pseudopod formation of the tumor cell and necessary for its invasion and metastasis." (PMID 24040244, 2013). "This is because antigen priming is required for generation of tumor-infiltrating Tregs in addition to simple loss of CCR7, which normally occurs during differentiation of T cells in secondary lymphoid tissues." (PMID 22292042, 2012). "The frequent expression of CCR7 in HNSCC and association with lymph node metastasis suggests that CCR7 expression provides tumor cells with a mechanism for direct lymph node infiltration." (PMID 24212639, 2011). "Concerning WHO classification, the high expression ratio of CCR7 also was highly significantly associated with higher tumor UIUC stages." (PMID 21548969, 2011).